THBS4 (thrombospondin 4)
Diseases named in the same sentence as THBS4 in open-access papers (continued):
Sharing a sentence is not in itself a finding about the gene and the disease.
tumor (continued). "In line with this, gene silencing by hypermethylation and an association with more invasive tumors was recently reported for INA and THBS4 in other tumor entities." (PMID 35008203, 2021). "TGF-β1 increases the THBS4 expression and affects angiogenesis to promote tumor growth in endothelial cells." (PMID 34804159, 2021). "The remarkable activation of THBS4 expression in tumors is most likely regulated through the interactions of invading tumor cells with stromal fibroblasts in the local microenvironment." (PMID 34502094, 2021). "Recently, we found increased levels of THBS4, an ECM protein, is highly associated with PDGFRβ expression in tumor tissues when compared to normal tissues of colon cancer patients." (PMID 34502094, 2021). "Bioinformatic analysis of THBS4 expression profiles through The Cancer Genome Atlas (TCGA) indicated that THBS4 was significantly increased in the majority of tumor types." (PMID 34390328, 2021). "Further analysis revealed that the expression of interstitial THBS4 was positively correlated with the blood vessel density in tumor tissues." (PMID 34390328, 2021). "Tumor vascular permeability fluorescence imaging in vivo demonstrated that THBS4-knockdown H. pylori-pretreated BM-MSCs demonstrated a weakened neovascularization density compared with H. pylori-pretreated NC BM-MSCs." (PMID 34390328, 2021). "Our data indicated that THBS4 derived from BM-MSCs plays a facilitative role in regulating tumor angiogenesis in H. pylori-related GC in vitro and in vivo." (PMID 34390328, 2021). "Methylated TCGA KIRC based candidate CpG loci in INA, NHLH2, and THBS4 that are possibly associated with RCC metastasis were evaluated by pyrosequencing in 154 paired normal adjacent and primary tumor tissues, as well as in 202 metastatic tissues." (PMID 35008203, 2021). "This study showed that PDGFRβ was overexpressed and that THBS4 was significantly increased in the tumor tissue when compared to normal colon tissue in CRC patients." (PMID 32899998, 2020). "Upon 5‐aza treatment, a down‐regulated expression of two tumour suppressors, THBS4 and PTPRG were restored, as well as a potential epigenetic diagnostic marker CMTM28 and miR200c involved in activation of Notch pathways in CTCL." (PMID 32794659, 2020). "The role of TGFβ in CRC is also of interest, as it has been shown to be an upstream signal of PDGFRβ in tumor cells, and is involved in angiogenesis through THBS4." (PMID 32899998, 2020). "A single study reported that the expression level of THBS4-003 (Thrombospondin 4) is significantly higher in PCa cells compared to non-tumor ones." (PMID 33349800, 2020). "The role of THBS4 in cancer has primarily been focused on tumor adhesion, migration, invasion, and angiogenesis while the role of PDGFRβ has been extensively studied in epithelial-mesenchymal transition (EMT) and metastasis." (PMID 32899998, 2020). "Thrombospondin-4 (THBS4), which is an extracellular matrix protein, also plays essential roles in the tumor microenvironment and mediates angiogenesis by transforming growth factor-β (TGFβ) signaling." (PMID 32899998, 2020). "Our analysis for each tumor stage revealed that the overall survival of the THBS4-high expression patients at Stage I and Stage III was significantly poorer than that of the patients with THBS4-low expression (p<0.001 and p = 0.001, respectively)." (PMID 31703077, 2019). "THBS4 was reported to stimulate the development of cancer, whereas other studies found that THBS4 acts as a tumor suppressor." (PMID 31703077, 2019). "It was recently reported that THBS4 is frequently expressed in the tumor stroma of some types of solid cancers such as breast cancer and prostate cancer." (PMID 31703077, 2019). "We also found that high THBS4 expression in tumor stroma was significantly poorer than that of the patients with low THBS4 expression." (PMID 31703077, 2019).
tumor (continued). "Stable over-expression of miR-142 significantly inhibited tumour growth in a xenograft tumour model through inhibiting THBS4 expression and tumor angiogenesis." (PMID 28177895, 2017). "In this study, by comparing the expression of THBS4 in HCC tumor samples with adjacent normal tissues using qRT-PCR, we found that tumor tissue had higher expression of THBS4 compared with adjacent normal tissue." (PMID 28177895, 2017). "While THBS4 is often overexpressed in HCC it has also been shown to inhibit tumor growth by mediating cell-to-cell and cell-to-matrix interactions." (PMID 28177895, 2017). "By analyzing HCC tumor samples in the TCGA database, we found that THBS4 expression was significantly higher in HCC tumor samples compared with adjacent normal samples." (PMID 28177895, 2017). "To further investigate the effect of miR-142 and THBS4 on tumor growth in vivo, we carried out xenograft studies by injecting HuH7-p-miR-control or HuH7-p-miR-142 cells into mice." (PMID 28177895, 2017). "Relative levels of THBS4 transcript expression in matched tumours and normal mucosa were also determined by quantitative RT-PCR." (PMID 20846368, 2010). "THBS4 exhibited methylation in both normal and tumour tissue and displayed a positive correlation with age." (PMID 20846368, 2010). "The greater the number of CIMP markers that were positive for methylation (PMR ≥10), the higher the level of THBS4 methylation, although the same proportion of CIMP-L and CIMP-H tumours demonstrated high THBS4 methylation." (PMID 20846368, 2010). "A subset of tumours did express THBS4 and evidently secrete the protein, observed as more intense staining of vesicular structures towards the luminal surface." (PMID 20846368, 2010). "Thrombospondin-4 is a putative tumour-suppressor gene that plays an integral role in mediating cellular processes such as cell attachment and migration." (PMID 20846368, 2010). "Tumours exhibited significantly higher levels of methylation than matched normal mucosa, and THBS4 methylation correlated with the CpG island methylator phenotype." (PMID 20846368, 2010). "In general, THBS4 protein was most likely to be seen at the luminal surface of normal crypts or tumour glands." (PMID 20846368, 2010). "This demonstrates that a large amount of THBS4 protein correlates with reduced cell growth, and strengthens the evidence supporting its role as a tumour suppressor gene." (PMID 20846368, 2010). "As a putative tumour-suppressor gene, methylation of the THBS4 promoter and silencing of its tumour-suppressor function is potentially pathogenic." (PMID 20846368, 2010). "In the context of tumor biology, THBS4 may contribute to tumor growth, proliferation, and migration, thereby promoting aggressive tumor behavior." (PMID 40303998, 2025). "Our findings suggest that THBS4 expression levels may influence the composition of CAF subsets in the tumor microenvironment." (PMID 40303998, 2025). "The specific regulatory mechanism of THBS4 in both normal and tumor tissues is not well understood, among which transforming growth factor β (TGF-β) signaling has been shown to be closely related, and it has been reported that SMAD3 is involved in the regulation of THBS4 by TGF-β." (PMID 40303998, 2025). "TRIB3 and FABP1 may interact with CEACAM5, PRAP1, GABRP and THBS4, and affect tumor immune microenvironment by regulating immune cells, and participate in the development and progression of GC." (PMID 34957220, 2021). "Bioinformatics analysis showed that TRIB3 and FABP1 may interact with CEACAM5, PRAP1, GABRP, and THBS4, and affect tumor immune microenvironment by regulating immune cells, and participate in the development and progression of GC." (PMID 34957220, 2021). "The emerging role of THBS4 in tumor-stroma interactions, particularly in GC, suggest that it may play an important role in the tumor microenvironment." (PMID 34390328, 2021).
tumor (continued). "However, how transcriptional and post-transcriptional levels of THBS4 are regulated in by interactions of tumor cells and stromal fibroblasts involved remain elusive." (PMID 34502094, 2021). "The results from the xenograft tumor model revealed that injection of H. pylori-pretreated BM-MSCs dramatically increased the growth of GC subcutaneous tumors, and these effects were also notably inhibited when THBS4 was silenced." (PMID 34390328, 2021). "This phenomenon might be caused by the Ca2+-binding domain of THBS4, and secreted THBS4 is known to regulate the tumor microenvironment through adhesion, migration, and attachment functions of ECM proteins." (PMID 32899998, 2020). "Compared to normal tissues, elevated levels of PDGFRβ and THBS4 were found in tumor tissues, which confirms our hypothesis that these two proteins are significantly associated with tumor development in CRC." (PMID 32899998, 2020). "The expression of THBS4 in each tumor was evaluated by immunohistochemistry." (PMID 31703077, 2019). "Furthermore, western blotting analysis of HCC tumor samples showed that expression of THBS4 was inversely correlated with miR-142." (PMID 28177895, 2017). "Given our initial observation that THBS4 expression correlated with tumor invasiveness, we investigated whether THBS4 regulated cellular migration and invasion in vitro." (PMID 28177895, 2017). "Immunohistochemical staining of THBS4 protein was assessed in normal and tumour specimens." (PMID 20846368, 2010). "Thus, while the average tumour PMR correlates well with an increasing number of markers positive for CIMP, there were an equal proportion of CIMP-L and CIMP-H tumours that showed high THBS4 methylation." (PMID 20846368, 2010). "Thus, while there was a trend towards lower THBS4 expression in tumours with a PMR greater than or equal to 10 having decreased expression, this difference was not significant." (PMID 20846368, 2010). "THBS4 may act as a tumour suppressor gene, demonstrated by its suppression of tumour colony formation in vitro." (PMID 20846368, 2010). "THBS4 may act as a tumour suppressor gene, evidenced by the dramatic repression of colony formation upon forced over-expression in CRC cell lines and its generally lower expression in cancers compared to normal mucosa." (PMID 20846368, 2010). "THBS4 expression was significantly lower in tumour tissue than in matched normal tissue." (PMID 20846368, 2010). "Further experiments are now required to investigate the mechanism of this reduced growth, which may be a direct result of THBS4-mediated tumour suppression or toxicity due to higher than physiologically normal levels of THBS4 protein." (PMID 20846368, 2010). "There was significantly higher expression of THBS4 in the normal mucosa compared to the tumour." (PMID 20846368, 2010). "Notably, THBS4 expression in some tumors is not directly secreted by tumor cells but rather by cancer-associated fibroblasts (CAF)." (PMID 40303998, 2025). "Interestingly, in most tumors, THBS4 promoted tumor progression." (PMID 40303998, 2025). "Multivariate analyses of the prognostic value of the S100A9/THBS4 predictor for the 3-year metastasis-free survival by a Cox regression model that includes potential confounding factors (including patient age and gender, tumor stage and history of tobacco smoking)." (PMID 38022675, 2023). "In contrast, NHLH2 and THBS4 could be analyzed independent from tumor histology." (PMID 35008203, 2021). "Additionally, it has been suggested that, because of rare genomic alterations in the THBS4 genes, a remarkable activation of THBS4 expression in tumors is most likely regulated through the interaction of invading tumor cells with stromal fibroblasts in the local microenvironment." (PMID 32899998, 2020). "However, THBS4 methylation in tumours was positively correlated with CIMP." (PMID 20846368, 2010).
tumor (continued). "ROC analysis showed good differentiation of the two tumor groups by expression level of GP6 and THBS4." (PMID 40303998, 2025). "Immunohistochemical analysis of THBS4 expression in LNM and NLNM PTMC tissues revealed more positive staining in the tumor cytoplasm of the former, while fibroblasts in the tumor mesenchyme were barely stained." (PMID 40303998, 2025). "ITGA6 is a transmembrane protein involved in cell surface adhesion and signaling as well as in the regulation of proliferation, tumor invasion, and metastasis; similar to THBS3 and THBS4, ITGA6 is also expressed in the skin of sheep." (PMID 39913466, 2025). "Generally, THBS1 was primarily found in fibroblasts, endothelial cells, and mononuclear macrophage cells, THBS3 was mostly expressed in fibroblasts, tumor cells and T cells, whereas THBS2, THBS4 and COMP were mainly found in fibroblasts." (PMID 38827236, 2024). "THBS4 (Thrombospondin‐4) member of the ECM receptor interaction, focal adhesion and TGF‐β signaling pathway was reported as a tumor suppressor gene in the CRC." (PMID 38872418, 2024). "As depicted in UMAP plots, THBS2, THBS4 and COMP were primarily expressed by fibroblasts, while THBS3 was predominantly expressed by tumor cells and fibroblasts, and THBS1 was predominantly expressed by fibroblasts, monocyte-macrophages and endothelial cells." (PMID 38827236, 2024). "In this study, we characterized the expression of THBS4 and miR-142 in HCC cell lines and tumor samples." (PMID 28177895, 2017). "THBS4 expression normalised to ACTB was generally quite low in both peritumoural normal mucosa and in tumours." (PMID 20846368, 2010). "THBS4 promoter hypermethylation (PMR ≥10) was observed in 4/30 (13.3%) CIMP-NEG tumours, 4/11 (36.4%) CIMP-L tumours, and 5/14 (35.7%) CIMP-H tumours." (PMID 20846368, 2010). "THBS4 methylation in the tumours, as quantitatively measured by MethyLight, significantly increased with the increasing CIMP status of tumours." (PMID 20846368, 2010). "Based on previous studies and our results, we speculate that tumor cells and CAF in PTMC may be involved in bidirectional regulation through THBS4 and TGF-β signaling pathways, which needs to be further confirmed in in vitro and in vivo experiments." (PMID 40303998, 2025). "To analyze whether the candidate genes have tumor-specific hypermethylation, we measured 120, 141, and 132 corresponding pairs of adN and tumor tissue specimens for methylation of INA, NHLH2, and THBS4." (PMID 35008203, 2021). "The THBS4/integrin α2 axis promotes the migration and tube formation of endothelial cells by facilitating the PI3K/AKT pathway, which induces the formation of new tumor vessels in the H. pylori infection microenvironment." (PMID 34390328, 2021). "Immunohistochemical examination demonstrated that THBS4 protein was generally absent from normal epithelial cells and tumours, but was occasionally expressed at low levels in the cytoplasm towards the luminal surface in vesicular structures." (PMID 20846368, 2010). "Immunohistochemical localisation of THBS4 confirmed the absence of protein expression in the majority of tumours." (PMID 20846368, 2010). "Tumours with THBS4 PMR ≥10 appeared to have lower THBS4 expression, but this difference was not significant, according to the Wilcoxon Rank-sum (Mann-Whitney) analysis (p = 0.26, data not shown)." (PMID 20846368, 2010).
tumor (continued). "There was a trend towards decreased gene expression in tumours exhibiting high THBS4 methylation, but the correlation was not significant." (PMID 20846368, 2010). "In addition, we found that the expression at the RNA level of THBS4 together with S100A9 is an independent prognostic signature that remains predictive of metastasis despite confounding factors that include patient age, tobacco consumption and tumor stage." (PMID 38022675, 2023). "Using a PMR of 10 as a cut off, tumours were separated into THBS4 methylation positive (PMR ≥10) and THBS4 methylation negative (PMR < 10)." (PMID 20846368, 2010). "Furthermore, we divided the 30 HCC tumor samples into two groups according to whether they had vascular invasion or not and observed that the tumors that showed vascular invasion had higher expression of THBS4 than those tumors which did not exhibit vascular invasion." (PMID 28177895, 2017). "In addition, although NP mice exhibited significantly shorter tumor-free survival compared to N mice, and SAA1, SAA2, and THBS4 enhanced HER2/neu+ cancer cell proliferation in vitro, Ki67 staining of tumor sections did not reveal differences in proliferation between N and NP tumors." (PMID 41387465, 2025).